HIF1A (hypoxia inducible factor 1 subunit alpha)
Diseases named in the same sentence as HIF1A in open-access papers (continued):
Sharing a sentence is not in itself a finding about the gene and the disease.
tumor (continued). "In normal liver tissues (normoxia dominated), the USP14 protein level is lower than that of tumor tissues, and HIF1-α is lower expressed." (PMID 34420039, 2021). "Kruskal–Wallis rank sum test was used to analyze the difference of HIF-1α expression among clinical tumor stages." (PMID 33441708, 2021). "Hyperosmotic inducible factor 1 α (HIF1α) is a hypoxia marker that greatly influences malignant transformation and tumor metastasis." (PMID 34745938, 2021). "Elevated levels of HIF-1α are often found in tumors, which triggers neoangiogenesis that supplies nutrients and oxygen to the tumor mass by increasing the expression of angiogenic factors." (PMID 33842469, 2021). "HIF-1α expression was found with a significantly increased activity on the margin of tumor infiltration and necrosis surroundings and its accumulation in hypoxia further prompts epithelial-mesenchymal transition." (PMID 34329303, 2021). "Hirudo is also known to inhibit tumor angiogenesis by improving the tumor hypoxia microenvironment, reducing the mRNA and protein expression of HIF-1α, and contributing to the downregulation of VEGF mRNA expression." (PMID 33673020, 2021). "HIF-1α regulates a variety of tumor processes for adaptation, including metabolism, angiogenesis, invasion and cell proliferation." (PMID 34926270, 2021). "Intriguingly, HDAC4 deacetylates and stabilizes HIF1α, one of the central players of tumor progression and drug response." (PMID 34359722, 2021). "Further studies have shown that the combination of HIF-1α inhibitors and Ado-inhibiting tumor immune microenvironment regulatory drugs with ICIs has demonstrated promising efficacy in both preclinical and phase I/II clinical studies." (PMID 34012727, 2021). "HIF-2α expression has also been correlated with tumor growth and the presence of distant metastasis; moreover, both HIF-1α and HIF-2α expressions have been related to decreased overall survival." (PMID 34958428, 2021). "In hypoxic conditions, miR-205 upregulation causes HITT degradation and that allows YB-1 (Y-box binding protein) translational regulator binding on 5′UTR HIF-1α mRNA region leading to tumor angiogenesis." (PMID 33763348, 2021). "The effect of VDAs is related to tumor blood vessels’ destruction and the appearance of hypoxia in the central part of the tumors due to the activation of HIF-1α protein." (PMID 34439079, 2021). "Hypoxia-induced fibrosis can inhibit the infiltration of T cells into the tumor, and the continuous activation of hypoxia-inducible factor 1 alpha (HIF-1α) can negatively regulate the signal transduction function of T cell receptors." (PMID 34067040, 2021). "In addition, since hypoxia/HIF1α is implicated in many immunosuppressive mechanisms, it will be of interest to determine whether the combination CDKi/HSP90i treatment modulates the immune response for anti-tumor activities." (PMID 34686682, 2021). "Tumor-derived lactate is a potent inducer of HIF-1α, and lactate promotes immunosuppressive polarization of TAM in a HIF-1α-dependent manner." (PMID 34389031, 2021). "Treatment with a NO donor in combination with a PD-1/PD-1L therapy can potentially reverse this effect of HIF-1α on PD-L1 accumulation within the tumor." (PMID 33513777, 2021). "Hypoxia is common in fast-growing solid tumors, and Hif-1α is a key factor that helps tumor tissues adapt to the hypoxic microenvironment." (PMID 34540683, 2021). "In the PDX model, HIF1α was much more expressed in internal hypoxia tumor tissue than in external normoxia tumor." (PMID 33440739, 2021). "The gene expression of VEGF in tumor cells is controlled by HIF-1α, a transcription factor that is induced under hypoxic conditions." (PMID 35083006, 2021).
tumor (continued). "In mouse models of lung adenocarcinoma and melanoma, tumor-derived lactate pushes macrophages toward an anti-inflammatory phenotype and promotes tumor growth in a HIF-1α-dependent manner." (PMID 33670082, 2021). "Hypoxia-caused stresses induce chemoresistance and cancer survival through the activation of hypoxia-inducible factor 1α (HIF-1α), pro-survival ER stress, and protective autophagy and consequently perturb cancer therapy in the tumor microenvironment." (PMID 34948250, 2021). "On the basis of our study, VHL, SIRT4, HIF-1α, and HO-1 were genes related to a few tumor-related biological processes, including metabolism, cancer development, and cellular stress response." (PMID 34135317, 2021). "The drug inhibits RNA polymerase II-dependent transcription of mRNA by blocking the phosphorylation of its COOH-terminal domain, and thereby prevents global transcription including HIF-1α, leading to anti-tumor effects, confirmed in a clinical study." (PMID 34200019, 2021). "When tumor cells are under hypoxic conditions, HIF-1α is activated and regulates downstream pathways related to tumor development." (PMID 34540836, 2021). "The down-regulated HIF-1α in NSCLC cells is a part contributing to the repressive effects of methanol-ethyl acetate partitioned fraction from Magnolia grandiflora on tumor cell invasion and migration." (PMID 34044859, 2021). "In summary, our work unravels an IL-6-regulated cellular mechanism that controls Mφ-mediated tumor immunity through IL-10 and Stat3/HIF-1α/CD40 expression." (PMID 34103524, 2021). "Recent data showed that expression of HLA-G on tumor cells can be regulated by the transcription factor hypoxia-inducible factor 1α (HIF-1α) and that HIF-1α regulates MDSC function during murine pregnancy." (PMID 35111157, 2021). "HIF1α is known to regulate a global adaptive transcriptional response to hypoxia and, as such, it is a critical oncoprotein in promoting tumor growth via regulating transcriptomic networks involved in angiogenesis, metabolism, and therapy resistance." (PMID 34272356, 2021). "Consistent with our observations, HIF1α directly promotes EMT and tumor-associated macrophages can also drive EMT in tumors." (PMID 34407185, 2021). "The already reported anti-tumor effects of HIF-1α inhibition are in part the result of a perturbation of the molecular circuits sustaining microenvironment-mediated protection from apoptosis." (PMID 34207596, 2021). "Lysyl oxidase (LOX) has been proven to act as a tumour promoter and regulate by HIF-1α in ovarian cancer." (PMID 35004308, 2021). "Particularly in ccRCC, HIF-1α appears to function as a tumor suppressor, and its expression is often silenced, whereas HIF-2α acts as a driver of ccRCC progression." (PMID 34931765, 2021). "To investigate the importance of HIF-1α in healthy B cells in the CLL tumor microenvironment, we adoptively transferred Eμ-TCL1 CLL cells into mice lacking HIF-1α in healthy B cells, CD19Cre/WT Hif1afl/fl." (PMID 34572746, 2021). "Taken together, our study is in agreement the work of Flonta and colleagues who proposed several possible mechanisms of MB function in tumor cells, that is as regulator of oxidative stress, O2 transporter to overcome hypoxia, or by regulation of HIF-1α." (PMID 34671319, 2021). "Under hypoxia, HIF-1α plays an important role in the transcription of genes involved in angiogenesis, tumor growth, invasion, metastasis, and glucose metabolism." (PMID 34220956, 2021). "Elevated lactate levels, aberrant mTOR signaling, and the hypoxic conditions of the tumor microenvironment can all activate HIF-1α, which has been shown to impair NK cell effector function in a variety of settings." (PMID 33670082, 2021). "Von Hippel Lindau (VHL), a tumor suppressor, targets HIF1α/2α by ubiquitination involving E3 ligase to proteasomal degradation." (PMID 35145899, 2021).
tumor (continued). "In the tumour microenvironment, the overexpression of PD-L1 is closely related to the increased expression of HIF-1α and the activation of NF-κB." (PMID 34256773, 2021). "The sensitivity analyses, which assessed HIF-1α positivity based on percent positive of tumor cells, yielded similar results to the analyses assessing HIF-1α expression based on the H-score." (PMID 34736510, 2021). "Bevacizumab, an anti-VEGF antibody to reduce tumor angiogenesis, was found to induce tumor hypoxia and upregulation of hypoxia-inducible factor-1α (HIF1α), resulting in hypoxia-induced resistance to bevacizumab in tumors." (PMID 34948368, 2021). "In response to hypoxia, cells activate the transcription factor hypoxia-inducible factor-1α (HIF-1α) that, in turn, activates numerous hypoxia inducible genes and thus promotes angiogenesis to boost proliferation of tumor vasculature." (PMID 33573362, 2021). "The molecular mechanism resides in a decrease of the HIF-1α protein inside the tumor area, inhibiting the blood vessel formation inside the developing tumors without binding to the MT1." (PMID 34209857, 2021). "Loss of HIF-1α in CD8 T cells was shown to reduce activation, tumor infiltration and tumor cell killing, and alter tumor vascularization." (PMID 34676055, 2021). "The results showed that HIF1α downregulation not only directly inhibited tumor cell generation but also promoted ROS production in the tumor environment, thereby enhancing PDT-mediated apoptosis." (PMID 34834367, 2021). "In CLL, HIF-1α fosters different tumor-promoting mechanisms: it mediates the adaptation of leukemic cells to hypoxia, functions as a pro-survival factor and is implicated in drug-resistance mechanisms." (PMID 34207596, 2021). "For instance, use of these agents for cancer chemotherapy increases tumor hypoxia via a hypoxia-inducible factor-1α (HIF-1α) signaling pathway." (PMID 34790659, 2021). "ARTN2 is associated with hypoxia response and acts as a dimerization partner of hypoxia-inducible factor 1α (HIF1α), which acts is adaptive stress response as well as angiogenesis required for tumor growth and metastasis." (PMID 33924679, 2021). "In a preclinical mouse study, selective deletion of HIF-1α in T cells led to increased tumor growth and decreased T cell tumor infiltration, survival, and effector function, measured by production of TNFα and IFNγ." (PMID 34868044, 2021). "Inhibition of the expression or activity of HIF-1α can directly or indirectly enhance the therapeutic responsiveness of tumour cells." (PMID 35004308, 2021). "Decreasing HIF-1α expression is an efficient strategy for inhibiting tumor cell survival and invasion." (PMID 34784907, 2021). "There is increasing evidence that HIF1α mediates tumor metastasis, angiogenesis and the development of resistance to various therapeutic modalities." (PMID 34763667, 2021). "HIF1A/VEGF signaling pathway also has been found to be involved in mediating SC tumor growth and angiogenesis under hypoxic conditions." (PMID 34621671, 2021). "HIF-1α is widely expressed in human tumors, and higher expression has been observed in advanced tumors with increased tumor volume." (PMID 34930376, 2021). "HIF1A is an important transcription factor related to tumor cell survival, angiogenesis and invasion." (PMID 34838012, 2021). "As highlighted in recent papers, hypoxia through HIF-1α activation participates to increase cell stemness in tumor mass by promoting the EMT and addressing the GBM fate toward malignancy." (PMID 34440169, 2021). "Activation of HIF-1α can recruit MDSCs to the primary tumor site by enhancing the expression of chemokine (C–C motif) ligand 26 in tumor cells, which can further inhibit antitumor T cell effector function." (PMID 34737746, 2021). "In humans, upregulation of HIF-1α affects NK cell function rather negatively by downregulating the expression of activating receptors involved in tumor killing." (PMID 33920906, 2021).
tumor (continued). "Combinatorial therapy achieved the most effective control of both mesenchymal and proneural tumors, although monotherapy alone targeted to Smad3 or HIF-1α hindered tumor growth near the detection limits." (PMID 34707087, 2021). "Studies report the interaction of HIF-1α and Hsp70 in modulating mitochondrial functions, tumor cell metabolism, and survival." (PMID 33716751, 2021). "HIF-1α also promotes the differentiation of tumor MDSCs into more potent suppressors of T cell activity." (PMID 34831183, 2021). "With increased tumor volume, cells in the middle of the tumor experience hypoxia, and the expression of HIF-1α is significantly increased." (PMID 34930376, 2021). "Similar to tumor cells, the HIF-1α signaling pathway also has the ability to regulate the migration of MSCs." (PMID 34631221, 2021). "During acute hypoxic stress, tumor cells adapt their metabolism through HIF-1α, which modulates glycolytic genes, making them less dependent on oxygen and increasing survival." (PMID 34900673, 2021). "FOXC1 activates genes heralding EMT and tumor migration, it is a positive regulator of cancer stem cell function, and appears to be a downstream target of HIF1α-signaling, i.e., the FOXC1 expression enhances the adaptation to tumor hypoxia." (PMID 34659373, 2021). "Using in vivo experiments, we examined the tumor growth and survival time of Saos-2-bearing mice treated with a combination of chemotherapeutic agents and a HIF1α inhibitor." (PMID 34763667, 2021). "First, tumor cells were detected by flow cytometry of bone marrow from the tibiae and femora from Hif1αf/f PyMT+ and Hif1α−/− PyMT+ mice based on epithelial cell adhesion molecule (EpCAM) positivity." (PMID 34556788, 2021). "HIF-1α is induced by intratumoural hypoxia, which plays a critical role in tumour progression and metastasis, leading to treatment failure and even mortality." (PMID 34172725, 2021). "Consistent with the results obtained from the rodent tumor tissues, the expression of HIF‐1α in clinical samples decreased substantially after treatments with HBO three times, the collagen content decreased too." (PMID 34085419, 2021). "Among which HIF2α has been considered as an oncogene to promote ccRCC tumorigenesis, while HIF1α exhibits a tumor suppressor role." (PMID 34321604, 2021). "Hypoxia, through HIF1α stabilization, is known to induce pro-tumor phenotypes, including a collective-to-amoeboid transition in cell migration, increased in vimentin expression, and increased migration of 4T1 cells." (PMID 33859337, 2021). "It has been previously demonstrated that KDACIs such as TSA can degrade HIF-1α stimulated by hypoxia with variable efficiency in different tumor cell lines." (PMID 33806075, 2021). "In the tumor microenvironment, incomplete embolization results in relative hypoxia and, thereby, elevates the expression of hypoxia-inducible factor-1α (HIF-1α)." (PMID 33505496, 2021). "While it does have anti-tumor effects and increased patient survival, it can also induce increased expression of hypoxia-related genes HIF-1α and VEGF." (PMID 33919732, 2021). "HIF-1α of tumor cells was more highly expressed in the stroma-high subgroup than in the stroma-low subgroup." (PMID 33810015, 2021). "Together, these data indicate that HIF1α is indispensable for LOXL2-mediated tumor-promoting functions in PDAC cells." (PMID 34836938, 2021). "ST6GAL1 endows resistance of cancer cells to gefitinib (EGFR inhibitor) and trastuzumab (anti-ErbB2 antibody) and also confers tumor cell resistance against hypoxia via enhancing hypoxia-inducible factor-1α (HIF-1α) expression." (PMID 34745942, 2021). "Tumor cells overcome low oxygen tension by activating several pathways, among which HIF1α signaling plays a vital role in cancer progression." (PMID 34763667, 2021).
tumor (continued). "Meanwhile, down-regulation of HIF-1α/fatty acid synthase co-axis was shown to combat tumor growth in mammary gland carcinoma by activating PHD-2." (PMID 35280255, 2021). "In this tumor, XBP-1 gene signature is strongly associated with HIF-1α gene signature, and they correlate with a lower relapse-free survival." (PMID 33423689, 2021). "The levels of HIF1α progressively increase with tumor progression in the MMTV-PyMT model, mimicking human patients and making it an ideal model to study the roles of hypoxia on breast cancer progression, metastasis and therapy." (PMID 33235291, 2021). "We report here the higher expression of Cav-1 within the peri-necrotic and pseudo-palisading areas of the GB tumour, areas also expressing high levels of HIF-1α factor." (PMID 34490102, 2021). "This tool was used to visualize HIF-1α protein accumulation in vivo, in mice with xenograft tumor implants." (PMID 33466454, 2021). "HIF-1α additionally upregulates tumor autophagy, which is critical for tumor cell survival in the harsh metabolic conditions of the TME as it allows tumor cells to recycle damaged organelles and proteins into metabolic substrates for energy generation." (PMID 34868044, 2021). "Nowadays, HIF1a is considered as a tumor suppressor that inhibits tumor growth, while HIF2a generally acts as an oncogene that directly promotes cell proliferation and metabolic alterations." (PMID 33463050, 2021). "HIF-1α expression in primary tumour tissues and the presence of bone metastasis was investigated in a retrospective cohort study of 96 patients with NSCLC." (PMID 34298636, 2021). "HIF-1α and its regulatory pathways possibly represent appealing targets in the quest for novel strategies to overcome microenvironment-mediated tumor support in CLL." (PMID 34207596, 2021). "This resulted in much attention toward the inhibition of HIF-1α expression in suppressing chemoresistance, while elevating the anti-tumor activity of chemotherapeutic agents." (PMID 32784981, 2020). "In the oxygen-glucose deprivation microenvironment, HIF-1α is a master regulator that plays crucial roles for tumor survival." (PMID 32308748, 2020). "In cells treated with 5 μM DFO, LAT1 expression was restored in all cell lines treated with siRNA (P = 0.102 for T98G cells, P = 0.004 for HSC-3 cells, P = 0.030 for MCF-7 cells), revealing that HIF-1α suppresses LAT1 expression in hypoxic tumor cells." (PMID 32367141, 2020). "Interplay between HIF-1α and Ras/Src oncogenes in tumor microenvironment in the regulation of PFK1 and PFK2 isoenzymes has been suggested as being a contributor to human cancer cell proliferation and survival." (PMID 32252351, 2020). "In short, CTHRC1 can affect the expression of HIF-1α, which is not only related to lymphangiogenesis but also closely related to tumor progression and invasion." (PMID 32848510, 2020). "The significant role of HIF-1α in tumor development was first identified due to its abundant overexpression in a broad range of tumor types and its participation in critical aspects of tumor initiation and progression." (PMID 31931758, 2020). "Numerous studies reported that HIF-1α synthesis, or its decreased degradation, can be modulated by different tumor suppressor genes and oncogenes, among which there are many proteins encoded by transforming viruses." (PMID 31947661, 2020).